MARK3 (microtubule affinity regulating kinase 3)
Diseases named in the same sentence as MARK3 in open-access papers:
MARK3 is named in the same sentence as 31 diseases in open-access papers, as found by Europe PMC text mining. Sharing a sentence is not in itself a finding about the gene and the disease. The quoted sentences say what the papers report.
breast carcinoma (5 papers, 2021 to 2025). "MARK3 downregulation is linked to cancer cell survival and chemoresistance, similar to findings in colorectal and breast cancers." (PMID 40136361, 2025). "In comparison to the normal samples (M0), AS switches occurring in patients with breast cancer metastasis (M1) were significantly different in COMMD4_AS2, MARK3, and MATR3." (PMID 36725888, 2023). "In Basal-like breast cancer, both MARK1 and MARK3 were positively associated with patient survival in the pre-chemotherapy group but negatively associated with survival post-chemotherapy." (PMID 34084284, 2021). "To further confirm the presence of IDR in the protein regions encoded by breast-cancer-associated AS events, we analyzed ADD3, PACSIN2, DIAPH1, MARK3, and MAP3K7 protein sequences with the PONDR web tool, a predictor of natural disordered regions." (PMID 34202984, 2021). "We found that METTL3 depletion promoted exon inclusion of the alternative exons of GNAS, MATR3, POLDIP3 and promoted skipping of the alternative exons of COMMD4, MARK3 and the non-m6A modified transcripts FASTK and EXOC7 in both breast cancer cell lines." (PMID 36725888, 2023). "In this study, we found a higher PSI value in breast cancer patients than in normal samples for COMMD4_AS2, GNAS, MATR3, RHOC and COMMD4_AS1, whereas the PSI value was lower for MARK3, POLDIP3 and FASTK." (PMID 36725888, 2023). "In Luminal A breast cancers, the positive survival effects of AMPK, MARK3, PAK1, BRSK1, SNRK, and QSK are maintained in the pre-chemotherapy but not in the post-chemotherapy cohorts." (PMID 34084284, 2021). "Although we found variabilities along the stages, which reflects the heterogeneity of this disease, COMMD4_AS2, MARK3, MATR3, POLDIP3, COMMD4_AS1, and GNAS underwent AS switches in almost all stages of breast cancer, while RHOC displayed significant AS switches during stage IIB." (PMID 36725888, 2023). "We observed that the AS events for COMMD4_AS2, GNAS, MATR3,COMMD4_AS1 and RHOC displayed a significant higher PSI value in cancer patients than in normal samples, while the PSI values were significantly lower for MARK3, POLDIP3 and FASTK in patients with breast cancer." (PMID 36725888, 2023). "Finally, in our functional analysis of aberrantly expressed AS exons in breast cancer cells and tissues (PACSIN2 exon 8, DIAPH1 exon 2, MARK3 exon 16, ADD3 exon 13, and MAP3K7 exon 12), we found that dysregulated cassette exons encode for IDRs." (PMID 34202984, 2021). "Importantly, we were also able to confirm, by RT-PCR, the aberrant AS regulation of PACSIN2, DIAPH1, MARK3, ADD3, MAP3K7, and MARK2 in RNA extracts from two human tumor breast cancer samples tissues and two non-pathological tissues." (PMID 34202984, 2021).
colorectal cancer (3 papers, 2011 to 2025). A primary or metastatic malignant neoplasm that affects the colon or rectum. "C-TAK1 (MARK3/Par-1a/p78) has been implicated in pancreatic, liver, and colorectal cancers, hippocampal function, and metabolism." (PMID 22206009, 2011). "This supports the role of MARK3 in inhibiting endometrial cancer cell proliferation, possibly through mechanisms of cell cycle arrest, a feature observed in other cancers like ovarian and colorectal cancer." (PMID 40136361, 2025).
Obesity (3 papers, 2012 to 2022). Accumulation of substantial excess body fat. "The Mark3-/- mice are protected against high-fat diet-induced obesity and display attenuated weight gain." (PMID 31266200, 2019). "In addition, knockout mice (MARK3−/−) were protected against high-fat diet induced obesity and displayed attenuated weight gain." (PMID 35873681, 2022). "Mice with disrupted genes for Mark2 or Mark3, which are other members of the AMPK family, have been found to be resistant to diet-induced obesity due to enhanced glucose-utilization in the brown adipose tissue." (PMID 22662228, 2012).
osteoporosis (3 papers, 2011 to 2024). A condition of reduced bone mass, with decreased cortical thickness and a decrease in the number and size of the trabeculae of cancellous bone (but normal chemical composition), resulting in increased fracture incidence. "In osteoporosis, the variant rs11623869 in MARK3 has been associated with bone mineral density and low-trauma fractures." (PMID 38715801, 2024). "In previous studies, MARK3 has been associated with bone mineral density (BMD), an indicator for osteoporosis." (PMID 36498562, 2022).
cervical cancer (1 paper, 2025). A primary or metastatic malignant neoplasm involving the cervix. "Prior studies have demonstrated the prognostic and functional significance of MARK3 in various cancers, including breast, ovarian, colorectal, and cervical cancers, but its role in endometrial cancer has remained unexplored until now." (PMID 40136361, 2025).
endometrial carcinoma (1 paper, 2025). A malignant tumor arising from the epithelium that lines the cavity of the uterine body. "The findings indicate that MARK3 may be pivotal in the molecular pathways underlying endometrial cancer growth." (PMID 40136361, 2025). "RT-qPCR analysis demonstrated a notable elevation in MARK3 mRNA expression in overexpressed endometrial cancer cell lines relative to normal endometrial cancer cell lines." (PMID 40136361, 2025). "The CCK-8 assay provided evidence for MARK3 overexpression and inhibited the proliferation of endometrial cancer cells, demonstrating a significant decrease in the proliferation rate of MARK3-overexpressing cells relative to control groups." (PMID 40136361, 2025). "A circular map was employed to illustrate the coordinated expression patterns of MARK3 and its co-expressed genes in TCGA endometrial cancer samples." (PMID 40136361, 2025). "The bioinformatics results highlight the significance of MARK3 in the course of endometrial cancer, positioning it as a viable candidate for additional functional validation and therapeutic targeting." (PMID 40136361, 2025). "The findings indicate MARK3 as a potential therapeutic target for strategies designed to disrupt the survival mechanisms of endometrial cancer cells." (PMID 40136361, 2025). "This research presents new evidence regarding the function of MARK3 in endometrial cancer, showing its complex impact on cancer cell dynamics through regulation of proliferation, apoptosis, and migration." (PMID 40136361, 2025). "By exploring the role of MARK3 in endometrial cancer cell, we aimed to gain a deeper understanding of the pathogenesis of EC and shed light upon discovering novel therapeutic options." (PMID 40136361, 2025). "Western blot analysis was conducted to assess the impact of MARK3 overexpression on critical regulatory proteins in endometrial cancer cell lines, Ishikawa and HEC-1B." (PMID 40136361, 2025). "RT-qPCR analysis demonstrated elevated MARK3 expression in overexpression MARK3 endometrial cancer cells compared to control groups." (PMID 40136361, 2025). "Bioinformatics analysis reinforces the relevance of MARK3 in endometrial cancer, offering new insights into its clinical significance." (PMID 40136361, 2025). "Further study will be necessary to ascertain the molecular mechanisms related to MARK3’s role in endometrial cancer as well as assess its clinical importance for predicting patient outcomes and informing treatment approaches." (PMID 40136361, 2025). "This research investigates the functional role of microtubule affinity-regulating kinase 3 (MARK3) in endometrial cancer for the first time." (PMID 40136361, 2025). "The findings indicate that MARK3 overexpression significantly affects critical cellular processes, including survival and migration in endometrial cancer cells." (PMID 40136361, 2025). "Our findings highlight the significant role of MARK3 in regulating essential aspects of endometrial cancer progression, such as proliferation, apoptosis, and migration." (PMID 40136361, 2025). "The findings from experimental assays and bioinformatics analyses strongly indicate that MARK3 may serve as a prognostic biomarker and therapeutic target in endometrial cancer." (PMID 40136361, 2025). "The results emphasize the influence of MARK3 on endometrial cancer." (PMID 40136361, 2025). "This study investigated the role of MARK3 in endometrial cancer." (PMID 40136361, 2025). "This suggests that MARK3 may serve as a prognostic biomarker and therapeutic target in endometrial cancer." (PMID 40136361, 2025). "Modulating these pathways may provide a novel approach to personalized treatment strategies for patients with endometrial cancer through MARK3." (PMID 40136361, 2025). "The observed effects of reduced proliferation and decreased migration indicate that MARK3 may serve as a potential therapeutic target for endometrial cancer." (PMID 40136361, 2025).
endometrial carcinoma (continued). "Microtubule affinity-regulating kinase 3 (MARK3) has been identified as a potential candidate owing to its established prognostic significance in various cancers; however, its function in endometrial cancer (EC) is not yet well understood." (PMID 40136361, 2025). "Endometrial cancer cell lines, Ishikawa and HEC-1B, were utilized to evaluate the functional effects of MARK3 overexpression on critical cellular processes including proliferation and migration." (PMID 40136361, 2025).
migraine (1 paper, 2023). "Therefore, the potential role of MARK3 in migraine chronification may also be via regulation of HDACs." (PMID 38087366, 2023).
myelofibrosis (1 paper, 2023). A partial or complete replacement of the bone marrow stroma by fibrous tissue. "MARK2 and MARK3 have been approved as drug targets for the treatment of cancer and myelofibrosis." (PMID 37730114, 2023).
otosclerosis (1 paper, 2023). Formation of spongy bone in the labyrinth capsule which can progress toward the stapes (stapedial fixation) or anteriorly toward the cochlea leading to conductive, sensorineural, or mixed hearing loss. "Otosclerosis colocalized genetically with the expression of BANF1, MARK3 and SUPT3H in the highest number of tissues (14, 8 and 6, respectively), while the highest causal posterior probability was observed for TELO2 (9.5%), ZNRD2 (6.3%), EHBP1L1 (6.0%)." (PMID 36653343, 2023).
ovarian carcinoma (1 paper, 2022). A malignant neoplasm originating from the surface ovarian epithelium. "Taken together, our results indicated that MARK3 inhibited tumor cell proliferation and angiogenesis in ovarian cancer cells partly through the repression of AP-1 and YAP/TAZ/TEAD target genes." (PMID 35017636, 2022). "We also validated that MARK3 expression was decreased at the protein level in several ovarian cancer cell lines." (PMID 35017636, 2022). "RT-qPCR revealed that MARK3 mRNA expression was indeed downregulated in both ovarian cancer cell lines and clinical tissues of HGSOC." (PMID 35017636, 2022). "MARK3 overexpression suppresses cell proliferation and angiogenesis of ovarian cancer cells." (PMID 35017636, 2022).
proteinopathies (1 paper, 2025). "The effect of MARK3 APA and increased tau S262 phosphorylation on microtubule dynamics in TDP-43 proteinopathies should be the focus of future studies." (PMID 40454469, 2025).
sarcoma (1 paper, 2025). A usually aggressive malignant neoplasm of the soft tissue or bone. "Interestingly, a recent study reported that concomitant inhibition of both MARK2 and MARK3 is required to prevent YAP/TAZ function in diverse carcinoma and sarcoma contexts, highlighting the redundant nature of MARK family members." (PMID 40869130, 2025).
schwannoma (1 paper, 2021). A benign, usually encapsulated slow growing tumor composed of Schwann cells. "Similarly, the non-RTK PTK2/FAK and the serine-threonine kinases GAK, RPS6KA3/RSK2, and MARK3 were also found to be greatly suppressed in brigatinib-treated schwannoma cells." (PMID 34264955, 2021).
skin cutaneous melanoma (1 paper, 2022). "MARK3 mutations were frequently observed in uterine corpus endometrial carcinoma and skin cutaneous melanoma." (PMID 35017636, 2022).
cancer (9 papers, 2021 to 2025). A tumor composed of atypical neoplastic, often pleomorphic cells that invade other tissues. "This aligns with findings in other cancers, suggesting that MARK3 is associated with reduced cellular proliferation and enhanced cell cycle regulation." (PMID 40136361, 2025). "Dysregulation of MARK3 has been identified in multiple cancers and has been proven to be associated with tumor progression, metastasis, and treatment resistant." (PMID 40136361, 2025). "Gene enrichment analysis indicated that MARK3 is linked to essential cancer-related pathways, such as cell cycle regulation, apoptosis, and cell migration." (PMID 40136361, 2025). "Since HGSOC is a cancer type with a low frequency of point mutations, the occurrence of MARK3 mutations in HGSOCs was restrictive." (PMID 35017636, 2022). "However, in contrast to the functions of the other MARK family kinases, the cancer-associated upregulation of MARK3 is rarely reported." (PMID 35017636, 2022). "Last, gene mutation profiles of MARK3 across 22 cancer types were summarized from the TCGA project." (PMID 35017636, 2022). "This study systematically evaluates the functional role of MARK3 in endothelial cells, enhancing the understanding of its mechanistic contributions to cancer biology and offering insights into potential clinical applications." (PMID 40136361, 2025). "Dysregulation of MARK3 expression has been found to correlate with cancer progression and survival outcomes across numerous cancer types, such as breast, ovarian, colorectal, and endometrial." (PMID 40136361, 2025). "Prior research has established the regulation of AKT and apoptotic proteins by MARK3, highlighting its potential significance in cancer cell survival dynamics." (PMID 40136361, 2025). "This study represents the inaugural investigation into the functional role of MARK3 in endothelial cell progression, thereby enhancing our comprehension of its mechanistic influence on cancer biology and its implications for personalized therapy." (PMID 40136361, 2025). "Lastly, since highly downregulated DEGs such as PLAU, CTGF and CRYAB are known to promote angiogenesis in cancer, the in vivo tumor-suppressive effects of MARK3 were investigated via a mouse xenograft experiment using MARK3-inducible OVCAR3 cells." (PMID 35017636, 2022). "MARK3 may inhibit cancer cell survival through the modulation of PI3K/AKT/mTOR pathway, thereby inhibiting tumor progression." (PMID 40136361, 2025). "Intriguingly, immunohistochemical staining showed that MARK3 was strongly detected in the cell membrane and cytoplasm of HFTSECs, and STICs; however, its presence was diminished in primary HGSOCs, suggesting that the expression of MARK3 was repressed at a later stage of cancer development." (PMID 35017636, 2022). "Analogous to these results, it was hypothesized that the depletion of MARK3 rendered cancer cells vulnerable to metabolic stress." (PMID 35017636, 2022). "Additionally, it may be reasonable for cancer cells to diminish such MARK3 function to enhance metabolism and cell proliferation." (PMID 35017636, 2022). "Microtubule affinity-regulating kinase 3 (MARK3), has become an important target in cancer research." (PMID 40136361, 2025). "However, we focused our attention on PACSIN2, DIAPH1, MARK3, ADD3, MAP3K7, and MARK2 cassette exons as these events were validated in both normal and cancer cell lines and in non-pathological and tumor breast specimens." (PMID 34202984, 2021).
tumor (4 papers, 2021 to 2025). "Our findings demonstrate that MARK3 plays a significant role in regulating cellular processes critical for tumor progression, such as proliferation, apoptosis, and migration." (PMID 40136361, 2025). "Our results suggest that the tumor-suppressive effects of MARK3 were derived not only from CDC25 signaling but also from AP-1 signaling, which reportedly caused G1/S phase arrest." (PMID 35017636, 2022). "This indicates that MARK3 overexpression may inhibit the activation of the PI3K/AKT/mTOR signaling pathway, which is associated with cell survival, tumor progression, and resistance to therapeutic interventions." (PMID 40136361, 2025). "Correlation analysis revealed multiple genes exhibiting substantial positive correlations with MARK3 (correlation coefficient > 0.6, p-value < 0.05), suggesting that these genes may possess analogous regulatory mechanisms or biological processes essential to tumor development." (PMID 40136361, 2025). "Subcutaneously transplanted mouse tumors (without interrupting the endogenous MARK3 expression) of MARK3 overexpressed OVCAR3 cells exhibited significantly smaller tumor growth than control tumors." (PMID 35017636, 2022). "We confirmed an aberrant increase of cassette exon skipping in tumor specimens for PACSIN2 exon 8, DIAPH1 exon 2, FGFR1OP2 exon 4, MARK3 exon 16, DST exon 93, LMO7 exon 10, and RBM5 exon 7, whereas ADD3 exon 13, MAP3K7 exon 12, and MARK2 exon 15 were preferentially included in tumor specimens." (PMID 34202984, 2021).
infection (2 papers, 2010 to 2022). The state of being infected such as from the introduction of a foreign agent such as serum, vaccine, antigenic substance or organism. "We previously identified MARK1, MARK2 and MARK3 kinases as interaction partners of Orf9b35 and ongoing studies will reveal their role in infection and the innate response." (PMID 34942634, 2022).
MARK3 also shares sentences with these, for which no sentence is quoted: Alzheimer disease (1 paper); breast tumor (1); COVID-19 (1); frontotemporal lobar degeneration (1); glioma (1); Headache (1); Hypoglycemia (1); infectious disease (1); intraepithelial neoplasia (1); melanoma (1); psychiatric disorder (1); schizophrenia (1); serous ovarian carcinoma (1); uterine corpus endometrial carcinoma (1).